MERTK (MER proto-oncogene, tyrosine kinase)
Diseases named in the same sentence as MERTK in open-access papers (continued):
Sharing a sentence is not in itself a finding about the gene and the disease.
tumor (continued). "MerTK can induce intrinsic and adaptive resistance of Axl-targeted agents, which advocates a dual targeting of Axl and MerTK for the hindrance of downstream signaling and tumor growth." (PMID 32370748, 2020). "Activation of Axl/MerTK on tumor cells results in induction and maintenance of a mesenchymal-like tumor cell phenotype." (PMID 32087708, 2020). "The proto-oncogenic potential of AXL and MERTK was identified immediately upon their cloning from tumor cell lines." (PMID 31775787, 2019). "There was a positive correlation between miR-375 levels and MERTK expression in tumor sections with Pearson’s r = 0.67 and p < 0.001." (PMID 30850595, 2019). "In the tumor microenvironment, Gas6 signaling can regulate a variety of pro-tumorigenic cellular functions and increased expression of Gas6 and MerTK predicts poor prognosis in many types of cancer." (PMID 31903163, 2019). "Inhibition of MerTK on leukocytes decreases tumor growth and metastasis in in vivo models of breast cancer, melanoma and colon cancer." (PMID 31088471, 2019). "The anti-tumor activity of MerTK mAbs is planned using surrogate models and human MerTK transgenic mice." (PMID 30400822, 2018). "Here, for the first time, our data showed that ectopic MerTK expression was seen in a large proportion of MCL tumor samples and four of six MCL cell lines." (PMID 29554921, 2018). "Tumor-resident Mo-DCs are characterized by their high expression of CD11b, CD64, and MerTK and are predominantly considered suppressors of anti-tumor immunity." (PMID 30345015, 2018). "Further, efferocytosis upregulates MerTK, Axl, and Tyro3 expression and activity on tumor macrophages and DCs, promoting polarization towards an immunosuppressive phenotype." (PMID 30187085, 2018). "TYRO3 is a member of the TAM (TYRO3, AXL, MERTK) family of transmembrane receptor tyrosine kinases, which share overlapping functions in tumorigenesis and suppression of anti-tumor immunity." (PMID 30501104, 2018). "IHC assays revealed that phosphorylated MerTK was significantly reduced in tumor tissues from Z-138-xenograft models treated with 50 mg/kg UNC2250 and 75 mg/kg compared to that in the vehicle-treated group." (PMID 29554921, 2018). "Target validation studies, suggest that MerTK inhibition is a viable strategy for decreasing tumor burden in preclinical models." (PMID 29285287, 2017). "In fact, PLX treatment vigorously induced MerTK expression in xenograft tumours, which was robustly inhibited upon inhibition of autophagy with CQ." (PMID 29050198, 2017). "As hematopoietic cells produce MERTK, bone marrow reconstitution systems were also used to assess the effect of MERTK deletion on tumor cells." (PMID 29230082, 2017). "Many studies have used shRNA to show critical oncogenic roles for MerTK in a variety of tumor types." (PMID 29285287, 2017). "The aim of this study was to identify a subgroup of GC patients with MerTK tumor overexpression, and to evaluate MerTK as a potential therapeutic target in this disease." (PMID 29228560, 2017). "In line with recent studies, MerTK is emerging as an important regulator in tumorigenesis and metastasis, possibly playing a unique role at the crossroads between tumour cells and the host immune system." (PMID 29050198, 2017). "Among many novel associations, MERTK was identified as a predictive marker for resistance towards MEK1/2 inhibitors and immunohistochemistry of 1,074 CRC tumours confirmed MERTK as a prognostic survival marker." (PMID 29101300, 2017). "In orthotopic cell line and patient-derived xenograft models, MERTK inhibition decreased tumor burden and prolonged survival, implicating MERTK as a therapeutic target." (PMID 27834816, 2016). "Previous studies demonstrated reduced tumor cell viability and tumor growth in response to inhibition of MERTK using shRNA or a MERTK specific antibody." (PMID 27783662, 2016).
tumor (continued). "Cases with medium or high MERTK expression were significantly enriched in all types of tumor tissue compared to normal mucosa (p < 0.001)." (PMID 27081701, 2016). "In the TCGA cohort there also was a trend towards higher MERTK mRNA levels with 29 % of primary tumor samples having an expression above the 85th quantile as compared to normal mucosa (p = 0.16)." (PMID 27081701, 2016). "Genetic inhibition of MERTK using small hairpin RNA (shRNA) or small interfering RNA (siRNA) resulted in delayed tumor development, decreased tumor cell proliferation, and induction of apoptosis in GBM and other cancers." (PMID 27783662, 2016). "The aim of our study was to investigate the biological significance of MERTK and to evaluate its potential as a novel therapeutic target in this dismal tumor entity." (PMID 27081701, 2016). "One of them is UNC1062, which inhibits MERTK phosphorylation and colony formation in different tumor cell lines." (PMID 27081701, 2016). "The mechanisms by which AXL inhibition exerts anti-tumor effects are similar to those described for MERTK inhibition in AML and ALL." (PMID 27834816, 2016). "This is supported by data from co-cultures of macrophages and HSV-TK expressing tumor cells treated with ganciclovir to induce apoptosis in which treatment with anti-MerTK resulted in impaired efferocytosis." (PMID 26674639, 2015). "The specific and concentrated inhibition of MerTK resulted in profoundly inhibited tumor development, both in the flank and the intracranial orthotopic models." (PMID 24658326, 2014). "Foretinib treatment in vivo abolished MerTK phosphorylation and reduced tumor growth 3-4 fold in a subcutaneous mouse model." (PMID 24658326, 2014). "Furthermore, the AXL/MERTK signaling blockade sensitized tumor cells to anti–programmed cell death 1 (anti–PD-1) treatment." (PMID 39774471, 2025). "Together, these data indicate that tumor-bound MerTK may serve as a predictor of response to ICI in TNBC, and that further investigation into its use as a biomarker may be warranted." (PMID 40391157, 2025). "Given that TNBCs are relatively cold and MerTK is associated with tumor progression in TNBC, we initially hypothesized that tumor-bound MerTK promotes a cold TIME in TNBC, which may lead to resistance to ICIs." (PMID 40391157, 2025). "For example, activation of MERTK can lead to Akt-dependent upregulation of PD-L1 on tumour cells." (PMID 40088262, 2025). "Studies have shown that the role of MERTK in NF-κb signalling is twofold: in tumour cells, MERTK activates NF-κb to enhance survival signalling, whereas in myeloid immune cells, including macrophages, it inhibits NF-κb, which in turn inhibits the proinflammatory cytokine response." (PMID 40088262, 2025). "Blockade of MerTK can suppress the survival, invasion, angiogenesis, and metastasis of tumor cells." (PMID 41195524, 2025). "To confirm whether efferocytosis is affected by MERTK inhibition, we quantified efferocytic macrophages in tumours, draining lymph nodes and the spleen of treated animals." (PMID 39788719, 2025). "In TME, the presence of MERTK in tumour cells may further enhance their independence from growth factors, enable the advancement of the cell cycle, and stimulate tumour growth." (PMID 40088262, 2025). "Immunotherapeutic strategies that block the interaction sites between Hsp70, TLR2, and MerTK could be advantageous for cancer treatment by disrupting the immunosuppressive communication between tumor cells and immune cells." (PMID 39941817, 2025). "However, in the middle and high MerTK expression groups (OD 0.01-0.05 and OD >0.05, respectively), increasing levels of all four analytes are detected in the tumor compartment." (PMID 40391157, 2025). "For example, small molecules or antibodies could be designed to bind to these flexible DOT regions, preventing MERTK signaling and potentially enhancing anti-tumor immune responses in oncologic therapies." (PMID 39535659, 2025).
tumor (continued). "MerTK overexpression was associated with either unchanged or accelerated tumor growth in NCG mice, unchanged tumor growth in athymic nude mice, and significantly delayed tumor growth in BALB/c mice compared to vector control for both 4T1 and EMT6 tumor models." (PMID 40391157, 2025). "However, MERTK knockdown in sh‐PROS1 K1 cells reduced the tumor growth induced by PROS1‐overexpressing CAFs." (PMID 40433916, 2025). "We found intensive reciprocal interactions between TICs and immune-regulatory tumor-associated macrophages (Reg-TAMs) via growth arrest–specific 6/AXL receptor tyrosine kinase/MER proto-oncogene, tyrosine kinase (GAS6/AXL/MERTK) signaling pathways, which facilitated the immune escape of TICs." (PMID 39774471, 2025). "Additionally, IHC analysis corroborated the flow cytometry findings and showed increases in staining of CD8+ and CD4+ T cells, NK cells (NKp46), and macrophages (F4/80) in MerTK-overexpressing tumor sections relative to Vector control." (PMID 40391157, 2025). "Additionally, in vivo studies demonstrated that MOC2 tumor growth was more significantly impacted by the Axl/MerTK dual inhibitor INCB081776." (PMID 40149328, 2025). "Our data showing unchanged or accelerated growth of MerTK-overexpressing tumors in triple immunodeficient NCG mice lacking T cells, B cells, and natural killer (NK) cells and harboring low levels of macrophages and dendritic cells highlights the role of MerTK in promoting tumor growth." (PMID 40391157, 2025). "Second, drugs targeting the TAM receptor are being developed, including MerTK inhibitors and Axl inhibitors, which may have the potential to block efferocytosis in the tumor microenvironment." (PMID 39748782, 2025). "In addition, tumors overexpressing MerTK exhibited very high sensitivity to both aPDL1 and aCTLA4 therapies, leading to durable tumor control and, in some cases, complete tumor regression without recurrence." (PMID 40391157, 2025). "Therefore, the developmentof inhibitors targeting MerTK while avoiding inhibition of Tyro3 holdspromise to suppress tumor growth and alleviate immunosuppression withinthe tumor microenvironment, without inducing neurotoxicity." (PMID 40391976, 2025). "We found that WNT-activated malignant epithelial cells interacted intensively with immune-regulatory tumor-associated macrophages (Reg-TAMs) via the growth arrest–specific 6/AXL receptor tyrosine kinase/MER proto-oncogene, tyrosine kinase (GAS6/AXL/MERTK) pathway." (PMID 39774471, 2025). "Interestingly, the viability of suspended tumor cells was more vulnerable to MerTK inhibition, indicating that MerTK plays a vital role in maintaining cell viability in an anchorage‐independent manner." (PMID 38545840, 2024). "Additionally, ENG expression levels were positively correlated with MerTK in the TCGA primary TNBC tumor samples." (PMID 38791148, 2024). "Therefore, it is necessary to develop novel therapeutics that efficiently block pro-tumor MerTK in the periphery while sparing MerTK in the eyes." (PMID 38443968, 2024). "Furthermore, TNBC patients whose tumor contained high MerTK RNA expression levels tended to have reduced OS." (PMID 38791148, 2024). "Additionally, MerTK expression attenuated the response to neoadjuvant treatment, and its inhibition sensitized tumor cells to 5‐Fluorouracil (5‐FU)‐based chemotherapy in vitro." (PMID 38545840, 2024). "Furthermore, we showed that the inhibition of MerTK using knockdown or knockout strategies was followed by reduced cell viability, likely through a higher rate of apoptosis and, consequently, smaller tumor growth in vivo." (PMID 38545840, 2024). "Cancer cells are known to highly express ‘‘don't eat me’’ signals such as CD47 that help them escape efferocytosis, and MerTK may facilitate tumor growth in some cancerous conditions." (PMID 38341954, 2024).
tumor (continued). "Yet another context, such as negative regulation of anti-tumor immunity, may involve more complex MERTK activity affecting both phagocytosis of dead and dying tumor cells and anti-inflammatory signaling." (PMID 38791338, 2024). "Taken together, our data and others suggest that tumor expression of MerTK could be directing tumor cell proliferation, migration, and invasion in TNBC patients." (PMID 38791148, 2024). "Anti-MerTK antibodies potentiate anti-tumor immunity and decrease mammary tumor metastasis." (PMID 38779685, 2024). "MERTK promotes tumor growth by contributing to an immunosuppressive microenvironment." (PMID 39062902, 2024). "Our tumor growth data demonstrated that overexpressing MerTK in the SUM102 cell line could promote the growth of early-stage TNBC tumors in nude mice." (PMID 38791148, 2024). "Thus, agents targeting MERTK are expected to provide therapeutic activity via multiple mechanisms, including direct tumor cell killing, inhibition of metastasis, and activation of anti-tumor immunity." (PMID 39199601, 2024). "Notably, blockade of MerTK resulted in the accumulation of apoptotic cells within tumours and triggered a type I interferon response." (PMID 37491279, 2023). "Notably, tumor-infiltrated CD14+ cDCs express high levels of markers that are characteristic of tumor-associated macrophages (TAMs), such as CD206, MerTK and CD163, suggesting that these cells exhibit TAM-like protumoral functions." (PMID 36949244, 2023). "After peritumoral injection, the prepared mU@OMVs is easily recognized and phagocytized by TAMs, resulting in efficient inhibition of the phosphorylation of MerTK in TAMs, and then the efferocytosis blockade of apoptotic cells and the secondary necrosis of tumor cells." (PMID 36966130, 2023). "MDK/ALK/ALP and GAS/MERTK/AXL interactions between tumor cells and endothelial cells/fibroblasts may be potential therapeutic targets for PTC." (PMID 37733241, 2023). "Blocking the macrophage MerTK protein may increase antitumor immunity and induce tumor immunogenicity, a promising method for treating cancer." (PMID 37513975, 2023). "Interestingly, a recent study demonstrated that blocking MerTK suppressed the clearance of apoptotic tumor cells and promoted macrophage STING activation." (PMID 37422464, 2023). "As such, AXL and MERTK inhibitors might induce adverse effects at the systemic level, and physiological effects of the alteration of AXL and MERTK signaling could be highly tissue-specific and depend on tumor microenvironment." (PMID 37469409, 2023). "MerTK CAR M displays targeted anti-tumor function in both in-vitro and in-vivo." (PMID 38017494, 2023). "It was proposed that the absence of MERTK in tumor-associated macrophages prevents the phagocytosis and disposal of dead tumor cells, thereby increasing the availability of tumor antigen to DCs and triggering improved anti-tumor T cell immunity." (PMID 35969037, 2022). "Interestingly, the investigators noted variations in AXL and MERTK expression during tumor progression and treatment exposure." (PMID 35572601, 2022). "Interestingly, targeting MERTK in immune-host cells proved superior over Axl KO to increase the quality of the anti-tumor immune infiltrates when administered with anti-PD-1." (PMID 35572601, 2022). "Similarly, GAS6 and PROS1 were significantly increased, and there was a trend toward increased MERTK expression in tumor biopsies from patients with EGFRMT NSCLC after treatment with OSI." (PMID 35708914, 2022). "MERTK inhibition-dependent enhancement of anti-tumor immunity is likely to be contextual." (PMID 35969037, 2022). "Furthermore, triple therapy targeting MerTK and PD-1 after radiotherapy-induced abscopal anti-tumor immune responses indicates a possible use for targeting efferocytosis and the inflammasome post-radiotherapy." (PMID 36439171, 2022). "Indeed, inhibition of MERTK in the tumor microenvironment in Mertk−/− mice was sufficient to decrease tumor growth and metastasis." (PMID 34830794, 2021).
tumor (continued). "As PD-1 based immunotherapy is dependent on T cell-based immune responses, thorough investigations into how MERTK and other receptor tyrosine kinase inhibitors may affect an anti-tumor T cell immune responses are essential." (PMID 34835225, 2021). "This is further facilitated by tumor-associated macrophages, which exhibit a highly efferocytic and immunoregulatory phenotype, and which express high levels of MERTK that further enhance the non-immunogenic clearance of apoptotic cancer cells." (PMID 34065321, 2021). "The beneficial effect of MERTK inhibition appears to conflict with the need to engulf apoptotic cells for the purpose of presenting tumor-derived antigens to T cells, which is a critical step in generating a cytotoxic immune response against the tumor." (PMID 34065321, 2021). "Aside from its direct roles in tumor metastasis, MERTK may have additional functions in promoting metastasis through its role in negative regulation of the immune system." (PMID 33562150, 2021). "TAM RTK signaling in the suppression of natural killer cell activity has been demonstrated in promoted metastasis, while in MERTK knockout mice, it showed a pro-inflammatory state in the tumor microenvironment and resulted in the inhibition of tumor metastasis." (PMID 33562150, 2021). "In addition, MERTK expression was increased when NSCLC cell lines were treated with AXL inhibitor or AXL expression was inhibited using siRNA and dual inhibition of AXL and MERTK reduced cell expansion in vitro and tumor growth in vivo." (PMID 34830794, 2021). "Altogether, macrophages MerTK blockade could promote tumor immunogenicity and potentiate antitumor immunity, which represents a promising strategy for tumor immunotherapy." (PMID 33463063, 2021). "Indeed, blockade of MERTK or AXL using a specific antibody or treatment with sitravatinib or R428 synergized with anti-PD-1 or anti-PD-L1 therapy to enhance anti-tumor immune responses." (PMID 34830794, 2021). "Antibody blockade of the phagocytic receptor MER proto-oncogene tyrosine kinase (MerTK) prevents apoptotic tumor cell clearance by TAMs and mobilizes antitumor immunity via the transport of tumor-derived cyclic GMP-AMP into TAMs and the subsequent activation of STING-dependent type I IFN response." (PMID 33919979, 2021). "Although MERTK is not expressed in circulating monocytes, it is upregulated during the transformation of monocytes into tumor-associated macrophages, especially M2 macrophages." (PMID 33562150, 2021). "Therefore, it is postulated that MerTK inhibition can be used to both control tumor growth directly and convert an immunosuppressive tumor microenvironment into an antitumoral microenvironment more prone to response to immunotherapy." (PMID 33801886, 2021). "Specifically, these mutations are located on five tumor suppressors (SDHA, RB1CC1, PTCH1, DMBT1, BCR) and eight proto-oncogenes (MERTK, CSF1R, MYB, ROS1, PCM1, FGFR2, MYH11, BRCC3) and have an allele frequency lower than 0.01 in the Genome Aggregation Database (GnomAD)." (PMID 33466296, 2021). "Since M2 macrophages contribute to maintenance of the tumor immunosuppressive microenvironment that promotes drug resistance and immune escape through activation of the MERTK signaling pathway, targeting MERTK has become a potential therapeutic strategy for fighting NSCLC." (PMID 33562150, 2021). "Mouse studies show promising results where MERTK inhibition favors tumor regression." (PMID 31664482, 2020). "Moreover, increased expression of MerTK, Axl, and Tyro3 receptor kinases by efferocytic macrophages in the tumor microenvironment stimulates tumor metastasis and immune suppression through elevated secretion of immune suppressive cytokines." (PMID 32059476, 2020).